TNF (tumor necrosis factor)
Diseases named in the same sentence as TNF in open-access papers (continued):
Sharing a sentence is not in itself a finding about the gene and the disease.
tumor (continued). "These pathways include tumor necrosis factor alpha (TNFα) signaling, inflammatory response, IL2 and signal transducer and activator of transcription 5 (STAT5) signaling, and interferon-gamma (IFNγ) response, suggesting its involvement in anti-tumor immune response." (PMID 38515213, 2024). "Furthermore, we also noticed that TNF signaling pathway and IFN signaling pathway were both de-activated, which meant anti-tumor immune response might be inhibited." (PMID 38184626, 2024). "TNF-α, through the activation of Tumor Necrosis Factor Receptor 1 (TNFR1) signaling, induces the upregulation of adhesion molecules on blood vessels and can prime and recruit CD8-positive T cells to infiltrate the tumor tissue via activation of Tumor Necrosis Factor Receptor 2 (TNFR2)." (PMID 39650654, 2024). "IL-1β signaling in tumor cells recruits monocytes, triggering the IL-1β + TAM state that drives inflammatory reprogramming in neighboring pancreatic ductal adenocarcinoma cells, enhancing synthesis of PGE2, TNF, and other factors that perpetuate the IL-1β + TAM state." (PMID 39068459, 2024). "Other cytokines, regardless of their proinflammatory (TNFα) or anti-inflammatory effects (IL-4, IL-10), may have diverse effects on promoting tumor growth." (PMID 39000195, 2024). "Therefore, it is very important to limit excessive postoperative concentrations of inflammatory mediators: TNFα, IL-8 and VEGF are key contributors to tumorigenesis, promoting a proinflammatory state aiding tumour growth as well as cell migration and neoangiogenesis." (PMID 38102395, 2024). "In addition, Rg3 could decrease the tumor volume and enhance anti-tumor T cell immunity as evidence by the upregulated expression of Granzyme B and perforin in CD8+T cells, along with elevated serum IL-2, IFN-g and TNF-a level in Rg3-treated mice." (PMID 39247194, 2024). "Taken together, these results indicated that TNFα-mediated PANX1 cleavage to promote ATP release may enhance cancer immunogenicity and promote chemotherapy-induced antitumor immunity by recruiting DCs and T cells to eradicate tumor cells." (PMID 38195677, 2024). "TNF-α shows its cytotoxicity, antiviral property and immune regulating functions by binding to the tumor necrosis factor receptor (TNFR) on target cells, enhancing the host’s immune function or acting with tumor vascular endothelial cells for vascular dysfunction." (PMID 39065636, 2024). "Interestingly, tumor or malaria infection did not significantly alter the serum level of IL-1β and TNF-α." (PMID 38774541, 2024). "However, the immunosuppressive microenvironment of GBM, characterized by factors such as interleukins, tumor necrosis factor-alpha (TNF-α), transforming growth factor-beta (TGF-β), and C-C motif chemokine ligands (CCLs), presents significant challenges for effective anti-tumor immune responses." (PMID 38732975, 2024). "However, exosomes derived from RAW264.7 cells and thalidomide (THD)-liposome co-ultrasonic extrusion can eliminate the expansion and proliferation of Treg cells induced by TNF in vitro, and reduce the survival and infiltration of Treg cells in the TME in vivo, so as to inhibit tumor growth." (PMID 38633106, 2024). "In vitro, Juz- or Gem/Juz-treated KPC tumor cells secreted significantly more macrophage-chemoattractant cytokines, e.g., CCL2, CCL20, and CXCL2, whilst Juz- and Gem/Juz-treated macrophages (MH-S) secreted cytokines of the M1 phenotype, e.g., IL6, TNF-α, and IL12." (PMID 39723364, 2024). "Interestingly, TNF‐α does not appear to be the only pathway mediating caspase‐8‐dependent mediation of tumour cell pyroptosis." (PMID 38652105, 2024). "For example, adoptive immune cell CAR-T cells and exosomes can reduce the expression of Ki-67, Gzms-B, IFN-γ and TNF-α, and improve CD8+ T cell invasion and activation, and exosomes containing CAR express high levels of cytotoxic molecules that significantly inhibit tumor growth." (PMID 38633106, 2024).
tumor (continued). "In this context, TNF-α secreted by macrophages may enhance activin A mRNA expression in ULM cells, potentially leading to excessive extracellular matrix production, tissue remodeling, and tumor growth." (PMID 39640883, 2024). "Furthermore, inflammation fosters an environment suitable for tumor growth by releasing specific cytokines, such as IL-6 and TNF-α, and growth factors like vascular endothelial growth factor (VEGF), which enhance cell proliferation and aid in tumor nourishment through angiogenesis." (PMID 38474160, 2024). "Studies have shown that cordycepin could inhibit TNF-signaling-induced MAPK activation, the expression of CFLAR, and regulate the CASP family and MMP family of proteins, thereby inhibiting tumor proliferation and metastasis while promoting apoptosis and autophagy in TNBC cells." (PMID 39000182, 2024). "Whether H. pylori–induced or not, lymphocytes and other tumor-infiltrating immune cells can nonetheless secrete proinflammatory cytokines such as TNFα and IFNγ." (PMID 39461475, 2024). "NK cells are another type of tumor-killing cells that can mediate tumor cell destruction through multiple mechanisms, including releasing perforin/granzyme pathways, secreting IFN-γ and TNF-α, and releasing antibody-dependent cell-mediated cytotoxicity (ADCC) pathways." (PMID 39076970, 2024). "Meanwhile, the effector cytokines tumor necrosis factor (TNF)‐α, interferon (IFN)‐γ, and interleukin (IL)‐2, secreted by both original CAR‐T cells and CAR‐ap‐enriched CAR‐T cells, could be significantly elevated when co‐incubated with tumor cells." (PMID 38148412, 2024). "Similarly, IL-2 contributes to a favorable response to ICI therapy by regulating leukocyte activity, interacting with antibodies, promoting hematopoiesis and tumor surveillance, and inducing NK cells to produce cytokines such as IFN-γ and tumor necrosis factor-α (TNF-α)." (PMID 39273605, 2024). "While generally thought to increase anti-tumor immunity, BRAF inhibitors may also exert competing effects such as driving tumor infiltration by macrophages, which can mediate resistance to BRAF inhibition through TNFα and VEGF." (PMID 38275291, 2024). "Within tumor cells, F. nucleatum induces pro-inflammatory signaling through the TNFα, NF-kB, and IL-6/IL-8 pathways and promotes tumor growth, EMT, metastasis, and therapy resistance, while also suppressing NK cell-mediated tumor cell killing and T cell infiltration into tumors." (PMID 39272898, 2024). "Additionally, IL-6, TNF-α, CXCL12, and leptin are considered to significantly promote tumor cell migration and proliferation, as well as inhibit apoptosis and activate autophagy, facilitating the development of tumor bone metastasis." (PMID 38571500, 2024). "In this work, we were able to identify the sites of the molecules in the proinflammatory cytokine TNF (tumor necrosis factor) and its TNFR1 (tumor necrosis factor receptor 1), which are necessary for the two-stage cytotoxic signal transduction required for tumor cell killing." (PMID 38612709, 2024). "When activated by lipopolysaccharide in vitro, METTL3-deficient macrophages could not produce the enough tumor necrosis factor (TNF)-α and contribute to tumor growth." (PMID 38346944, 2024). "In addition, CD34, EDIL3, and TPM3 were positively correlated with signaling pathways related to tumor immune response, invasion, and metastasis, particularly the IL6/JAK/STAT3, inflammatory response, TNF-α signaling via NF-kB, and epithelial-mesenchymal transition." (PMID 38840234, 2024). "The TNFα-CSG complex reduces tumor hardness and expands tumor vessels by activating immune cells to release ECM-degrading proteases, thereby enhancing tumor perfusion and augmenting the uptake of contrast agents (gadolinium and iron oxide nanoparticles) within the tumor." (PMID 38690275, 2024).
tumor (continued). "Suppression of BCL3 led to the upregulation of TNF-alpha and IL-6 and the downregulation of IL-10 in MDA-MB-231 triple-negative breast cancer cells, all of which would theoretically stimulate the recruitment and activation of immune cells within the tumour microenvironment." (PMID 38195591, 2024). "Moreover, SPP1 + Mac-derived TNF-α and IL-1β can promote the expression of OPN in both tumor cells and adjacent normal macrophages in turn, which may transform into SPP1 + Macs." (PMID 39726047, 2024). "Inflammatory cytokines TNF-α, IL-12 and IFNγ were increased especially in cell cultures with spleen cells from WT mice treated in vitro with BCG, but not with spleen cells from MyD88-/-, reinforcing the importance of MyD88 to induce cell death mechanisms and tumor control." (PMID 38835781, 2024). "Consequently, elevated amounts of TNF-α, IL-2, and IFN-γ were produced by CAR-T cells treatment only in CLDN18.2-positive cancer cells, where predominant CD8+ T cells were evidenced, corroborating a persistent and highly tumor-infiltrating CAR-T therapy." (PMID 38685033, 2024). "Programmed Death-Ligand 1 (PD-L1), Tumor Necrosis Factor (TNF), Fas Ligand (FasL) and TNF-Related Apoptosis-Inducing Ligand (TRAIL) are the main exosomal ligands and their receptors are located on the surface of tumor cells, becoming potential targets for cancer therapies." (PMID 39684236, 2024). "Similarly, in ovarian tumors, TNF-α is produced in large amounts, promoting a proinflammatory tumor microenvironment and activating NF-κB signaling, which induces the expression of chemokines including CCL8, CXCL13, and CXCL20 to accelerate tumor development." (PMID 38443657, 2024). "Additionally, CD300E significantly enhances pathways such as TNF-α signaling, inflammatory response pathways, IL6-JAK signaling, and epithelial-mesenchymal transition (EMT), all of which are documented to potentially promote tumor growth and metastasis." (PMID 39144140, 2024). "Interestingly, a study demonstrated that DCs loaded with the tumor derived exosomes (TEX) could promote T cell proliferation and enhance the release of multiple cytokines, including IFN-γ, IL-2, TNF-α, IL-10, and TGF-β." (PMID 38476233, 2024). "Moreover, tumour-infiltrating T cells in tumours treated with both RMC-4998 and RMC-4550 showed marked activation, proliferation, and expression of potential anti-tumour cytotoxic molecules, such as TNFα, IFNγ and Granzyme B." (PMID 39322643, 2024). "Factors like hypoxia, heterogeneous blood supply, and the presence of various cytokines (IL-1, IL-6, TNF-α, and IFN-γ) and enzymes can affect the activity or expression level of the therapeutic enzyme cytochrome P450, the distribution of the prodrug and its metabolites within the tumor." (PMID 38860140, 2024). "However, the fact that we could detect TNF‐α and IFN‐γ in the mouse serum at day 40 after treatment suggests that these CAR T cells are functional and release cytokines in the presence of the tumour." (PMID 39548594, 2024). "Additionally, we found more tumor-specific T cells with a stem-like (TCF1+ TIM3- PD1+) and a transitory (TCF1- TIM3+ CD101- PD1+) exhausted phenotype and more expressing effector molecules such as GzmB, IFNγ, and TNFα." (PMID 38646638, 2024). "We further explored the effects of Tug1 upregulation on the tumor immune microenvironments via flow cytometry and found that CD8+ T cells significantly increased and displayed stronger activation phenotypes with more production of IFN‐γ, IL‐2, and TNF‐α in sh‐Tug1 Hepa1‐6 cell‐bearing mice." (PMID 38981064, 2024). "It confirmed that reducing the membrane repair activity by targeting the molecular in the dsDNA-AIM2-ZBP1-ASC-RIPK1-RIPK3-CASP1-CASP8-GSDMD-GSDME pathway could increase the sensitivity of tumor cell membranes to Triton X-100, but reduce the sensitivity to IFN-γ and TNF-α." (PMID 38740747, 2024).
tumor (continued). "In addition, the results of functional assay indicated an increase in cytokine production (TNF-α), proliferation (Ki67), cytotoxicity (CD107a), and activation marker (CD25) in tumor-infiltrating CD8+ T cells of Rab37 KO group compared to those in tumors of WT mice." (PMID 38321486, 2024). "Furthermore, VCN-AgNPs increased the apoptotic proteins Bax and caspase-3, decreased the anti-apoptotic protein (Bcl-2), increased the inflammatory markers TNF-α and IL-1β, and inhibited angiogenesis by lowering VEGF levels in tumor tissues, all of which led to apoptosis." (PMID 39513869, 2024). "IFN-γ signaling in tumor cells can promote antigen and MHC class I molecule presentation to increase sensitivity by T cell-mediated direct killing, and indirectly contribute to cytotoxicity through the upregulation of the cytokine TNF-α, a member of the TNF superfamily." (PMID 38307835, 2024). "GI-irAE may be managed with anti-TNFα therapy without impacting tumor response and without dose-limiting toxic effects." (PMID 38995215, 2024). "For instance, TAM derived cytokines, such as IL‐6, IL‐1β, IL‐8, TNF‐α, CCL‐17, and CCL‐22 significantly contribute to proliferation of GC cells, immunosuppression and angiogenesis in TME through the mediation of immune surveillance which support tumor growth and metastasis as a result." (PMID 38349050, 2024). "γδ T cells can be triggered in an MHC-independent manner and directly kill tumor cells via various strategies, including NK-like cytotoxicity mechanism, antibody-dependent cell-mediated cytotoxicity (ADCC) effects, and secreting effector cytokines (e.g. IFN-γ, TNF-α)." (PMID 38904025, 2024). "Finally, the authors found that alloIgG isolated from healthy donors could similarly induce TADC activation in the presence of tumor necrosis factor alpha (TNF-α) and CD40 when cultured with tumor cells, validating the clinical performance of this approach." (PMID 38461238, 2024). "However, the absence of macrophages precludes TNF production in the microenvironment, thus preventing the immune system activation and the production of adequate T cells required to combat the tumor." (PMID 39627216, 2024). "As anticipated, upon encountering tumor antigens, the tumor-specific CTLs in conjunction with LPS-RGD-Nb36-DOX were able to quickly blockade the CTLA-4/B7 axis, as seen by increased expression of CD25, CD69, and CD62L as well as increased cytokine secretion (TNF-α, IFN-γ, and IL-2)." (PMID 38824143, 2024). "It has been suggested that the presence of TNF-α in the TME after immunotherapies like toll-like receptor agonists, DC vaccines, and tumor vaccines might elevate the expression of TNFR2 on T-regs, thereby boosting their ability to suppress anti-cancer immune responses." (PMID 39609700, 2024). "IFN-γ and TNF-α in the TME stimulate MSCs to secrete TGF-β1, which induces the EMT in melanoma, breast cancer, hepatocellular carcinoma, and pancreatic adenocarcinoma cells, and increases the resistance of tumor cells to apoptosis, enhancing the tumor invasive ability." (PMID 37588208, 2024). "Upon binding to the target antigen expressed on tumor cells, CAR-T cells undergo activation, leading to the secretion of cytotoxic molecules such as perforin and granzyme, as well as the release of pro-inflammatory cytokines such as interferon-gamma (IFN-γ) and tumor necrosis factor-alpha (TNF-α)." (PMID 39000281, 2024). "In summary, enrichment analysis results suggested that PHLDA2 may play a role in promoting tumor development by angiogenesis and EMT, and PHLDA2 may be involved in the regulation of the WNT signaling pathway,PI3K-AKT signaling pathway, TNF signaling pathway, and TGF-β signaling pathway." (PMID 38827322, 2024). "Overexpression of MCT11 resulted in accelerated functional exhaustion, as these T cells had decreased TNF and interferon γ (IFNγ) production, although no appreciable changes were observed in tumor infiltration or coinhibitory marker expression when compared with EV controls." (PMID 39516648, 2024).
tumor (continued). "Studies have revealed that valerate and butyrate significantly enhance the anti-tumour activity of cytotoxic T lymphocytes (CTLs) and chimeric antigen receptor (CAR) T cells by increasing the production of effector cytokines (CD25, IFN-γ and TNF-α) in CD8+ T cells." (PMID 38245525, 2024). "Therefore, it is speculated that a decrease in SLC20A1 expression could reduce the activation of the TNF/TNFR2 signaling pathway, thereby inhibiting Tregs, restoring tumor immune response, and eliminating the tumor." (PMID 38412319, 2024). "We found that concentrations of both IL-6 and TNFα were significantly high in the matched non-tumor and the matched tumor groups than healthy people (H) (P = 0.0289 and P < 0.001 for IL-6, and P = 0.001 and P < 0.001 for TNFα, respectively), whereas IL-1β was not (P = 0.7156 and P > 0.9999)." (PMID 38166062, 2024). "To understand molecular mechanisms of apoptosis induction by MASL treatments in tumor cells, we examined whether YM E2T, YM CL1T, and YM CL2T activated the expression levels of TNF-α, Fas, and FasL mRNA and protein that could contribute to the extrinsic pathways of apoptosis induction." (PMID 39683650, 2024). "Similarly, the semi-quantitative score of Treg infiltration at the tumor periphery did not correlate with the MFIs of IL-17 (Spearman’s ρ = -0.22, p = 0.30) or TNF-α (Spearman’s ρ = -0.23, p = 0.28)." (PMID 39650654, 2024). "Furthermore, CAR-M and CAR-shSIRPα-M exhibited increased secretion of IL-1β, IFN-γ, and TNF-α, regardless of tumor antigen stimulation." (PMID 39379603, 2024). "Inhibiting HOIP may increase the cytotoxicity of TNF and IFN-γ in tumor immunotherapy." (PMID 39223632, 2024). "On the other hand, the activation of signaling pathways such as NFκB by TNF by microglia, astrocytes, or glioma cells themselves can induce an increase in IL6 expression, which can activate the JAK/STAT3 pathway and contribute to tumor proliferation, migration, and invasion." (PMID 38248305, 2024). "Cytokines such as tumor necrosis factor (TNF)-α, interleukin (IL) family, and transforming growth factor (TGF)-β play an important role in angiogenesis, immune evasion, resistance to immunotherapy, and epithelial-mesenchymal transition (EMT) process responsible for tumor progression and metastasis." (PMID 36726580, 2023). "In fact, the permeability of HCMEC/D3 cells has been reported to be increased in stress conditions and pro-inflammatory cytokines and chemokines such as TNFα and CCL2 via signaling pathways as JNK, PKC or NFκB, which could be included in the EVs produced by tumor cell lines." (PMID 37297006, 2023). "Notably, tumor and cytotoxic immune cell co-culture assays confirmed that overexpression of circCRIM1 increased the proportion of tumor cell death and promoted the expression of Granzyme B, IFN-γ, and TNF-α of CD8+ T and natural killer (NK) cells." (PMID 36672208, 2023). "Therefore, the synergistic effect of TNF‐α and IFN‐γ on PANoptosis in tumor cells may be a significant mechanism to inhibit tumor growth, providing new targets for anticancer therapies." (PMID 38069556, 2023). "However, it is important to note that TNF-α blockade did not reduce the extent of tumor cell migration with supernatants from AMs with enhanced β-catenin to the same level as the control supernatants." (PMID 37092550, 2023). "Consistent with this, the levels of IFN-γ, TNF-α and IL-6 significantly increased in the serum of mice from the Bif@PAu-NPs + NIR + GM-CSF group compared to the other groups, indicating that a robust anti-tumor immune response triggered by the combination treatment." (PMID 37872620, 2023).